MRNIP (MRN complex interacting protein)
Description:
Plays a role in the cellular response to DNA damage and the maintenance of genome stability through its association with the MRN damage-sensing complex. Promotes chromatin loading and activity of the MRN complex to facilitate subsequent ATM-mediated DNA damage response signaling and DNA repair.
Synonyms: C5orf45; MGC65027; MGC78537; DKFZp686L2452; LOC51149
Tractability: Antibody: the Human Protein Atlas places it where antibodies can reach. PROTAC: ubiquitination databases record sites on it.
Gene: Protein-coding gene on chromosome 5 (179,835,133 to 179,862,173, reverse strand). Ensembl gene ENSG00000161010.
Subcellular location: Nucleus; Nucleus, nucleoplasm
Subcellular location (Human Protein Atlas): Cytosol; Plasma membrane
Gene Ontology:
Molecular function: chromatin binding; protein binding
Biological process: DNA damage response; mitotic G2 DNA damage checkpoint signaling; positive regulation of double-strand break repair via homologous recombination; positive regulation of protein kinase activity; protein localization to chromatin; regulation of double-strand break repair via nonhomologous end joining; response to ionizing radiation
Cellular component: Mre11 complex; nucleoplasm; nucleus
Genetic constraint (gnomAD): Loss-of-function variants: 26 observed, 20.79 expected, observed/expected ratio (o/e) 1.25, 90% interval 0.92 to 1.72. The upper end of that interval is the gene's LOEUF score, 1.72, which puts it in group 6 of 6, group 1 being the genes least tolerant of losing a copy. Missense variants: 408 observed, 384.55 expected, observed/expected ratio (o/e) 1.06, 90% interval 0.98 to 1.15. Synonymous variants: 176 observed, 149.22 expected, observed/expected ratio (o/e) 1.18, 90% interval 1.04 to 1.34.
Homologues: Orthologues: chimpanzee MRNIP (99% identical), macaque MRNIP (88% identical), rabbit MRNIP (60% identical), mouse Mrnip (51% identical), dog MRNIP (38% identical), zebrafish si:dkey-177p5.2 (24% identical).
Diseases named in the same sentence as MRNIP in open-access papers:
MRNIP is named in the same sentence as 10 diseases in open-access papers, as found by Europe PMC text mining. Sharing a sentence is not in itself a finding about the gene and the disease. The quoted sentences say what the papers report.
colorectal cancer (1 paper, 2022). A primary or metastatic malignant neoplasm that affects the colon or rectum. "Interestingly, MRNIP puncta were also detected in 3 out of 6 colorectal cancer (CRC) tissues, and existed in both γ-H2A.X positive and negative tumor cells." (PMID 35551189, 2022).
head and neck squamous cell carcinoma (1 paper, 2016). A squamous cell carcinoma that arises from any of the following anatomic sites: lip and oral cavity, nasal cavity, paranasal sinuses, pharynx, larynx, and salivary glands. "Analysis of online cancer genomics resources reveals that MRNIP is downregulated in several cancers, including head and neck squamous cell carcinoma, and amplified in 18% of renal clear cell carcinomas, which may be worth further study." (PMID 27568553, 2016).
Infertility (1 paper, 2022). "Finally, the presented data raise the possibility that impaired function of MRNIP could be a cause of infertility in humans and other species." (PMID 35920200, 2022).
male infertility (1 paper, 2024). The inability of the male to effect fertilization of an ovum after a specified period of unprotected intercourse. "The in vivo functionality of MRNIP has been recently evidenced by studies reporting impaired meiotic progression and male infertility in MRNIP KO mice – a phenotype shared with a number of other DNA repair and replication stress response factors." (PMID 38917325, 2024).
cancer (3 papers, 2016 to 2024). A tumor composed of atypical neoplastic, often pleomorphic cells that invade other tissues. "We assessed the prevalence of post-replicative gaps in cancer cells deficient in MRNIP, an MRE11 interactor that suppresses MRE11 exonuclease activity in vitro, and which prevents MRE11-dependent degradation of nascent DNA at stalled, reversed replication forks." (PMID 38917325, 2024). "Taken together, MRNIP condensates may serve as a surrogate for radioresistant cancer patients, and targeting MRNIP condensates may be a potential strategy for sensitizing tumor cells to radiotherapy." (PMID 35551189, 2022). "The effects of the genetic ablation of murine MRNIP on tumor incidence in mouse models of cancer and the incidence of tumors in aged MRNIP-null mice might therefore be worthy of investigation." (PMID 27568553, 2016).
tumor (2 papers, 2016 to 2022). "Additionally, knocking out MRNIP or abolishing the phase separation capacity of MRNIP via IDR1 deletion sensitized tumor cells to radiotherapy." (PMID 35551189, 2022). "Consistently, MRNIP depletion sensitized tumor cells to radiotherapy in an in vitro colony formation assay and re-expressing MRNIP in MRNIP-KO cells enhanced the radioresistance of tumor cells, whereas this effect was diminished by deleting IDR1." (PMID 35551189, 2022). "Additionally, MRNIP knockout sensitized tumor to radiotherapy in cellular and xenograft model." (PMID 35551189, 2022). "Most importantly, MRNIP puncta were also observed in both γ-H2A.X positive and negative tumor cells of CRC tissues." (PMID 35551189, 2022).
infection (1 paper, 2025). The state of being infected such as from the introduction of a foreign agent such as serum, vaccine, antigenic substance or organism. "The observed upregulation of MRNIP, RAD17, and SIRT1 in the Ml group indicates an active DDR alongside mechanisms that preserve genomic integrity and immune equilibrium during infection." (PMID 41333726, 2025). "MRNIP facilitates the proper assembly and function of the MRN complex, promoting efficient DNA damage repair, particularly in immune and endothelial cells under infection-induced stress." (PMID 41333726, 2025).
MRNIP also shares sentences with these, for which no sentence is quoted: cervical carcinoma (1 paper); proctitis (1); renal clear cell carcinomas (1).